VIM (vimentin)
Diseases named in the same sentence as VIM in open-access papers (continued):
Sharing a sentence is not in itself a finding about the gene and the disease.
Stroke (12 papers, 2012 to 2024). Sudden impairment of blood flow to a part of the brain due to occlusion or rupture of an artery to the brain. "The results showed that 6 genes filtered with optimal lambda value were identified as diagnostic characteristic genes in stroke, namely, HAS3, VIM, ZFP36L2, CPQ, F5, and PIK3CG." (PMID 38649659, 2024). "Examples of this type of measurement include levels of blood/tissue DES by mass spectrometry in the course of human heart failure, and blood vimentin in stroke, using the multiplexing Luminex protein platform." (PMID 37732119, 2023). "By 7 days, vimentin content is many times greater than that seen in equivalent tissue in the contralateral cortex or in the cortex prior to stroke." (PMID 34332596, 2021). "Consistent with this possibility, olomoucine treatment significantly reduced at least one major component of reactive astrogliosis, as evidenced by reductions in tissue vimentin content in peri-infarct tissue at 1 week after the stroke." (PMID 34332596, 2021). "Vimentin content was reduced by 30% in samples of tissue that included the infarct and neighbouring peri-infarct tissue at 7 days after stroke induction, when increases in expression of this protein are near maximal." (PMID 34332596, 2021). "When astrogliosis is attenuated by double knockout of GFAP and vimentin in mice that then underwent stroke of motor cortex, corticospinal axons only rarely crossed the midline and their length was significantly reduced compared to the axons in wild‐type mice." (PMID 31271523, 2019). "Vimentin expression was not remarkably high in this patient, which is surprising, since vimentin is upregulated in tissue from stroke patients." (PMID 22577599, 2012). "After taking the intersection of SCFA metabolism-related genes and the co-expression WGCNA modules of stroke, 10 SCFA-related hub genes were obtained, and 6 of them showed high diagnostic efficacy through LASSO regression and ROC analysis, including HAS3, VIM, ZFP36L2, CPQ, F5, and PIK3CG." (PMID 38649659, 2024). "However, the different outcome for the two cytoskeletal proteins might reflect a greater sensitivity of vimentin compared with GFAP content in detecting the treatment-induced changes following photothrombotic stroke." (PMID 34332596, 2021). "Mice subjected to a photothrombosis model of stroke, demonstrated a delay/impairment in neurological restoration in GFAP-/-Vim-/- mice indicating the importance of GFAP and vimentin in functional recovery and axonal remodeling following stroke." (PMID 38464735, 2023). "Five were the targetgenes of let-7 (ESM1, VIM, CDK6, NRAS, and KRAS), 3 of which (ESM1, VIM, and CDK6) were correlated with stroke based on published literatures." (PMID 26830013, 2016). "Vimentin is not normally expressed in astrocytes in mature brain but expression increases greatly in peri-infarct astrocytes during the first week after stroke." (PMID 34332596, 2021). "The content of both vimentin and GFAP at 7 days after stroke induction was substantially increased (to 210% and 137% respectively) in the samples from minocycline-treated rats compared with those injected with vehicle, indicating an increase in at least some aspects of reactive astrogliosis." (PMID 30626393, 2019). "Unlike vimentin expresson, the expression level of CNP was dramatically decreased in the stroke peri-infarct tissue in comparison to that in the contralateral normal tissue." (PMID 27841332, 2016).
systemic lupus erythematosus (12 papers, 2011 to 2025). An autoimmune multi-organ disease typically associated with vasculopathy and autoantibody production. "NET components such as dsDNA, histones, MPO, vimentin, and enolase have been associated to systemic pathology linked with disease entities such as small vessel vasculitis, systemic lupus erythematosus (SLE), disseminated intravascular coagulation, preeclampsia, and rheumatoid arthritis." (PMID 36839481, 2023). "Studies have found that curcumin inhibits the increase of matrix protein, glial fibrillary acidic protein, and vimentin in the hippocampus of lupus mice." (PMID 34557547, 2021). "This HLA allotype is shared with many systemic lupus erythematosus patients, suggesting that tertiary lymphoid structures using vimentin as an antigen could appear in several chronic inflammatory diseases." (PMID 32630064, 2020). "Post-translationally modified vimentin, e.g., phosphorylation, ubiquitination, carbamylation, and citrullination, has been extensively studied and shown to be involved in several diseases including RA, systemic lupus erythematosus, and ankylosing spondylitis." (PMID 32486012, 2020). "Additionally, recent studies found serum antibodies against carbamoylated vimentin in lupus, an example of yet another PTM that can enhance its immunogenicity." (PMID 32630064, 2020). "For example, vimentin, which is highly expressed on apoptotic T cells, has been detected at elevated levels in the serum of patients with rheumatoid arthritis, myocarditis, and systemic lupus erythematosus (SLE) probably deriving from T cell ApoEVs." (PMID 41357199, 2025).
urothelial carcinoma (12 papers, 2012 to 2025). A malignant neoplasm derived from the transitional epithelium of the urinary tract (urinary bladder, ureter, urethra, or renal pelvis). "First, the applicability of the Vimentin/POU4F2 methylation panel to other urothelial carcinomas—such as ureteral, renal pelvic, and upper tract tumors—remains to be determined." (PMID 41029537, 2025). "In high-grade urothelial carcinoma, reports in the literature on vimentin staining rates vary widely, ranging from 16% to 63%." (PMID 39451592, 2024). "In urothelial carcinoma, vimentin was detected only in the invasive front of some of the tumor samples and consequently was not considered a general BC marker." (PMID 35682984, 2022). "Our stainings showed positive vimentin staining in 29% (4/14) non-muscle infiltrating urothelial carcinomas and 80% (8/10) muscle-infiltrating urothelial carcinomas." (PMID 35439943, 2022). "IHC confirmed higher levels of cytokeratine 7 and lower levels of vimentin in non-muscle infiltrating low-grade urothelial cancer compared to muscle-infiltrating urothelial carcinoma." (PMID 35439943, 2022). "The muscle-infiltration status was distinguished via MSI by peptides from intermediate filaments such as cytokeratin 7 in non-muscle infiltrating carcinomas and vimentin in muscle-infiltrating urothelial carcinomas, which was confirmed by immunohistochemistry." (PMID 35439943, 2022). "The noninvasive urothelial carcinoma was positive for cytokeratin and E–cadherin, and negative for vimentin and ZEB1." (PMID 33032610, 2020). "Immunohistochemically, the noninvasive urothelial carcinoma was positive for cytokeratin and E–cadherin, whereas it was negative for vimentin." (PMID 33032610, 2020). "Because urothelial carcinoma cells are positive for CK, not for vimentin and CD10, it was not so difficult to make proper diagnosis with immunohistochemical markers." (PMID 23866935, 2013). "The urothelial carcinoma component within the ureter, the tumor cells were positive for cytokeratin, epithelial membrane antigen, E-Cadherin and negative for Vimentin, S-100 and CD99, enhancing the contrast of synchronous urothelial carcinoma from mesenchymal chondrosarcoma." (PMID 22999069, 2012).
hemangiopericytoma (11 papers, 2006 to 2024). An antiquated term that refers to benign or malignant mesenchymal neoplasms characterized by the presence of neoplastic spindle-shaped to round cells arranged around thin-walled branching vascular spaces. "Vimentin is the only marker expressed consistently in hemangiopericytoma." (PMID 22480217, 2012). "Hemangiopericytoma is one of the lesions that bears a close resemblance with SFT of soft tissues (fascicular pattern, fibrosis, and vimentin, CD34, and bcl2 immunoreactivity)." (PMID 17577399, 2007). "Immunohistochemical staining for vimentin and collagen type IV has also been proposed as a method to confirm hemangiopericytoma, in combination with negative stain for S-100, desmin, laminin, cytokeratins, and factor VIII-related antigen." (PMID 33204688, 2020). "Hemangiopericytomas are positive for vimentin and CD34, but negative for cytokeratin and smooth muscle markers." (PMID 24386948, 2014). "Hemangiopericytoma and solitary fibrous tumor show strong immunoreactivity for vimentin and CD34, but not EMA." (PMID 22934204, 2012). "Hemangiopericytomas are immunohistochemically positive for vimentin and CD34, but negative for cytokeratin and smooth muscle markers." (PMID 23050181, 2012). "Additionally, the staining for vimentin only and the absence of staghorn branching or hemangiopericytoma-like vascularity in the samples excluded the diagnosis of anaplastic carcinoma." (PMID 39420880, 2024). "Immunohistochemically, hemangiopericytomas are known to show a positive response to antibodies against vimentin and type IV collagen and a negative response to VIII-related antigen, S-100 protein, neuron specific enolase, carcinoembryonic antigen, desmins, laminin and cytokeratins." (PMID 16643656, 2006). "For example, a myofibroma can be distinguished by the central zonal phenomenon with vimentin and SMA stains, while a hemangiopericytoma does not present with lesional cells arranged in long bundles or fascicles, and is negative for smooth muscle-specific antibodies." (PMID 29238412, 2017).
Hyperglycemia (11 papers, 2016 to 2024). An increased concentration of glucose in the blood. "Mechanistically, the Western blot results analysis showed that ENO1 knockdown suppressed hyperglycemia-induced decreases in E-cadherin and increases in N-cadherin, Vimentin and Snail." (PMID 31889896, 2019). "The expression of mesenchymal markers N-cadherin and vimentin as well as transcription factor snail was stronger in hyperglycemia group." (PMID 27433288, 2016). "In contrast, the N-cadherin, vimentin, and snail staining in the cytoplasm of the cancer cells was significantly stronger in the hyperglycemia group than that in the euglycemia group." (PMID 27433288, 2016). "Reactive gliosis represents the response of Müller cells to hyperglycemia, a process characterized by a specific pathophysiological mechanism: hypertrophy, cellular proliferation, and increased intermediate filament proteins nestin, vimentin and glial fibrillary acidic protein (GFAP)." (PMID 28238189, 2017). "They respond to hyperglycemia by increasing the synthesis of glial fibrillary acid protein (GFAP) and vimentin and by producing inflammatory and angiogenic cytokines, such as hypoxia-inducible factor (HIF)-1." (PMID 36613769, 2022). "The changes in the levels of Snail, CD31, vimentin and α-SMA confirmed that hyperglycaemia induced EndMT, and the result coincided with our previous study." (PMID 35351142, 2022). "We found that silencing FASN reversed the effects of hyperglycaemia on the levels of EMT markers leading to increased expression of E-cadherin and decreased vimentin and fibronectin." (PMID 29331414, 2018). "We next evaluate the effects of hyperglycemia and PEG-CAT on the expression of E-cadherin, N-cadherin, vimentin, and snail at mRNA level by qRT-PCR." (PMID 27433288, 2016). "In contrast, mRNA levels of the mesenchymal marker Vimentin were solely increased by M1 macrophages and almost not affected by hyperglycemia in both PDEC lines." (PMID 34064969, 2021). "Attenuated lesion progression was accompanied with inhibition of hyperglycemia-induced TSP-1 expression and reduced protein O-glycosylation following CrP treatment; also, PCNA and vimentin (SMC synthetic marker) expression were reduced while SM-MHC (SMC contractile marker) levels were increased." (PMID 28345659, 2017). "To determine whether hyperglycemia-induced EMT was H2O2-related, we analyzed the expression of E-cadherin, N-cadherin, vimentin, and snail using Western blotting analysis." (PMID 27433288, 2016).
kidney cancer (11 papers, 2009 to 2025). Primary or metastatic malignant neoplasm involving the kidney. "Similar to the findings of our study, another study reported that VPA treatment decreased N‐cadherin and vimentin levels and increased E‐cadherin levels in kidney cancer cells." (PMID 40650414, 2025). "The rather low positivity rate in kidney cancers reflects the fact that these tumors have low cytokeratin levels and tend to express vimentin instead." (PMID 35946088, 2023). "Through western blot experiments, we found that TRIM33 overexpression in two kidney cancer cell lines resulted in the upregulation of the expression of E-cadherin and downregulation of the expression of N-cadherin and vimentin." (PMID 32908919, 2020). "Here, to investigate the role of PKM2 on EMT in kidney cancer cells, we examined the expression level of classical epithelial (E-cadherin) and mesenchymal (N-cadherin and vimentin) cells after PKM2 knockdown." (PMID 31717694, 2019). "Meanwhile, a lack of XCR1 genes inhibited EMT in kidney cancer, as evidenced by decreased protein levels of N-calmodulin and Vimentin and increased E-calmodulin." (PMID 37816979, 2023). "Also, the lack of the XCR1 genes inhibited EMT in kidney cancer, as evidenced by decreased protein levels of N-calmodulin and Vimentin and increased E-calmodulin." (PMID 37816979, 2023).
leiomyoma (11 papers, 2009 to 2026). A well-circumscribed benign smooth muscle neoplasm characterized by the presence of spindle cells with cigar-shaped nuclei, interlacing fascicles, and a whorled pattern. "On immunohistochemical evaluation, leiomyomas show positive staining for vimentin, smooth muscle actin, and desmin." (PMID 39280874, 2024). "Neurofibroma is rich in mucopolysaccharide, lacks a capsule, and has fewer axons; traumatic neuroma, while histologically similar to PEN and SCN, has inflammatory cells and scarring; and leiomyoma contains smooth muscle cells that stain positive for desmin and vimentin." (PMID 39463533, 2024). "Increased levels of α-SMA and decreased levels of vimentin and KRT-19 identified the leiomyoma tumor cells." (PMID 33777725, 2021). "To examine the effect of RSV on the expression of ECM in leiomyoma cells, we chose more representative ECM proteins as markers, such as fibronectin, collagen type 1, vimentin, and α-SMA." (PMID 31013842, 2019). "Human leiomyoma-derived fibroblasts (FB) were negative for desmin (center), suggestive of a non-muscle origin and positive for vimentin (upper left)." (PMID 20537183, 2010). "The leiomyoma was immunohistochemically positive for vimentin, α-smooth muscle actin, and desmin (1 case), but negative for cytokeratins, CD34, KIT, and PDGFRA." (PMID 27956961, 2009). "Fib-EXO increased the expression of vimentin, EZH2, DNMT1, TGF-β3, and c-MYC, and phosphorylated p65 protein, reduced COL1A1 and COL3A1 expression, and decreased miR-133a, miR-29, and miR-200c while increasing miR-21 in cultured myometrial smooth muscle cells, mirroring changes observed in fibroids." (PMID 42008339, 2026).
oncocytoma (11 papers, 2009 to 2024). "Recently, we identified a splice variant of vimentin, vimentin 3 (Vim3), as a specific marker for immunohistologic diagnosis differentiating oncocytoma from malignant renal cell carcinoma." (PMID 30116406, 2018). "Recent reports showing Vimentin positive oncocytomas seriously question the validity of this present diagnostic approach." (PMID 25944973, 2015). "Oncocytoma overexpress a truncated variant of Vimentin called Vim3." (PMID 30214689, 2018). "Thus, in this paper we analyzed the presence of Vim3 versus the full length Vimentin in RCCs, especially the eosinophilic variant of RCCs versus oncocytomas." (PMID 25944973, 2015). "After immune fluorescence for Vimentin FL (V9) as well as for Vim3 was performed, only the Vim3 staining showed positive areas, indicating that the second tumor type was indeed an oncocytoma." (PMID 25944973, 2015). "In conclusion, we present here a unique Vimentin isoform, Vim3, as a differential marker between malignant RCCs and oncocytoma." (PMID 25944973, 2015). "Our data present strong evidence that Vim3 is the isoform responsible for the so-called Vimentin positive oncocytomas described in the literature." (PMID 25944973, 2015). "The exact nature and mechanism of the “Vimentin positive oncocytomas” require further clarification." (PMID 25944973, 2015). "In particular, Vimentin positivity has been regarded as the major hallmark not only for RCC but also for differentiating them from their benign counterparts, the oncocytomas." (PMID 25944973, 2015). "For example, in the 50 gene signature that differentiated clear/papillary from chromophobe/oncocytoma, the clear cell marker Vimentin was identified." (PMID 21818257, 2011). "Of note, vimentin staining is also commonly positive in the areas of central scar in oncocytoma, similar to the increased staining for CK7 in these areas, which may be a diagnostic pitfall, as it differs from the expected results." (PMID 29090117, 2017). "However, a series of oncocytomas has recently been reported in which a Vimentin positivity has been observed, making the differentiation questionable, particularly in preoperative evaluation." (PMID 25944973, 2015). "Immunohistochemical examination revealed negative staining with vimentin (typical pattern characteristic for oncocytoma), whereas FLI 1 and CD99 were negative." (PMID 35276058, 2022). "In contrast, the reverse is true for oncocytomas: while their negativity for full length Vimentin is not surprising (and being a criteria for their identification), the levels for Vim3 are unexpectedly high." (PMID 25944973, 2015). "One case of collecting duct RCC showed focal positivity in stromal cells, however, oncocytomas (0/5) showed negative vimentin staining." (PMID 19558708, 2009). "Although CK7 staining may not be beyond the expected level of oncocytoma, findings such as negative vimentin staining and positive KIT staining generally argue against other considerations, such as papillary or clear cell renal cell carcinoma with eosinophilic cells." (PMID 29090117, 2017). "Immunohistochemically, oncocytoma is usually positive for EMA, CD117, and PAX8, but negative for CD10, alpha-inhibin and vimentin." (PMID 35220972, 2022).
spindle cell tumors (11 papers, 2006 to 2026). "Pathological findings of PSC have been reported as malignant spindle cell tumors on hematoxylin and eosin staining, and as cytokeratin (+) and vimentin (+) on immunohistochemistry." (PMID 41245941, 2025). "The epithelial component is usually urothelial, glandular or small cell component showing immunoreactivity for CKs, but the mesenchymal component is frequently an undifferentiated high-grade spindle cell neoplasm showing reactivity with vimentin." (PMID 20976205, 2010). "Histopathology revealed a malignant spindle cell tumor which was confirmed to be malignant peripheral nerve sheath tumor on the basis of immunopositivity for vimentin, neurone specific enolase and S-100." (PMID 18154670, 2007). "In latter studies, the same investigators postulated that the "vimentin+/CD34+ cell" is the precursor cell of all benign spindle cell neoplasm." (PMID 16859566, 2006). "Immunohistochemically, NF typically shows strong positivity for SMA and vimentin, with negativity for markers such as S-100 protein, desmin, and CD34, which helps differentiate NF from malignant spindle cell neoplasms, such as sarcomatous lesions." (PMID 41585341, 2026). "Immunohistochemical staining is also critical, with HPCs typically showing positivity for markers such as CD34, vimentin, CD99, and Bcl-2 and negativity for S100, which helps differentiate it from other spindle cell tumours." (PMID 39371697, 2024). "Immunohistochemistry frequently identifies SFT through positive staining for Vimentin, CD34, Bcl-2, and CD99, with CD34 serving as a critical marker to differentiate SFT from other spindle cell tumors." (PMID 39416460, 2024).